SLC12A5 (solute carrier family 12 member 5)
Diseases named in the same sentence as SLC12A5 in open-access papers (continued):
Sharing a sentence is not in itself a finding about the gene and the disease.
prostate adenocarcinoma (3 papers, 2022 to 2024). "Additionally, pan‐cancer survival analysis showed that SLC12A5 could also functioned as a risk factor for OS in prostate adenocarcinoma (PRAD), liver hepatocellular carcinoma (LIHC) and kidney renal clear cell carcinoma (KIRC)." (PMID 38685685, 2024). "In the present study, we demonstrated that expression of SLC12A5 was gradually increased in prostate adenocarcinoma, CRPC and NEPC tissues." (PMID 36609444, 2023). "When evaluating the datasets of CRPC and NEPC, we found that SLC12A5 expression was significantly upregulated in NEPC and CRPC compared with prostate adenocarcinoma samples." (PMID 36609444, 2023).
breast carcinoma (2 papers, 2022). "High SLC12A5 expression was suggested to predict poor survival in patients with bladder urothelial, colorectal and ovarian cancers, whereas the association direction in breast cancer was found the opposite in our study." (PMID 35729536, 2022).
hepatocellular carcinoma (2 papers, 2023 to 2024). A malignant tumor that arises from hepatocytes. "In summary, our study elucidates the significant role of SLC12A5 in regulating metabolic functions in hepatocellular carcinoma (HCC)." (PMID 38780503, 2024).
infantile epilepsy (2 papers, 2016 to 2022). "To investigate the possible involvement of SLC12A5 mutations in other types of infantile epilepsy, we also searched the WES data of 526 patients for biallelic SLC12A5 mutations, and examined an additional 141 patients by SLC12A5-targeted resequencing as a second cohort." (PMID 27436767, 2016). "Another patient (individual 4) with migrating multifocal seizures and compound heterozygous mutations [c.953G > C (p.W318S) and c.2242_2244del (p.S748del)] was identified by searching WES data from 526 patients and SLC12A5-targeted resequencing data from 141 patients with infantile epilepsy." (PMID 27436767, 2016).
hyperandrogenism (1 paper, 2025). Excessive secretion of androgens from the adrenal glands or gonads. "Notably, clinical evidence indicated that DIDO1 variants correlate with hyperandrogenism and central adiposity in females, while solute carrier family 12 member 5 (SLC12A5) mutations heighten T2DM risk in this population." (PMID 40429918, 2025).
lentivirus infection (1 paper, 2024). Virus diseases caused by the Lentivirus genus. "Based on these results, we conducted overexpression of SLC12A5 in LN229 and U87 cell line via lentivirus infection for further biological research." (PMID 38685685, 2024).
lymph node metastasis (1 paper, 2019). "High expression of the TWIST1-ceRNET components was significantly correlated with lymph node metastasis and advanced TNM staging (Lymph node metastasis: P = 0.025 for TWIST1, P = 0.005 for SLC12A5, P < 0.001 for ZFHX4; TNM stage: P = 0.008 for TWIST1, P = 0.015 for SLC12A5, P = 0.012 for ZFHX4;)." (PMID 31645542, 2019).
Neurodevelopmental delay (1 paper, 2022). "The reduced expression of Slc12a5 plays a key role in neurodevelopmental delay." (PMID 35237591, 2022).
prostate tumor (1 paper, 2023). "We explored SLC12A5 protein levels in 92 prostate tumor tissues and 52 adjacent normal prostate tissues using immunohistochemical staining." (PMID 36609444, 2023).
thyroid cancer (1 paper, 2025). "Hazard ratio analysis indicated that elevated F10 (HR = 1.006, p < 0.002), FOXD3 (HR = 1.14, p < 0.001), and SLC12A5 (HR = 1.003, p < 0.05) expression in patients with thyroid cancer was closely associated with poorer prognoses." (PMID 40785195, 2025). "Genetic markers, such as FOXD3 and SLC12A5, may serve as potential diagnostic biomarkers, facilitating more precise, personalized screening strategies for thyroid cancer." (PMID 40785195, 2025). "SLC12A5 has been confirmed to be overexpressed in thyroid cancer, making it an important player in the progression of this disease." (PMID 40785195, 2025).
neurological disorders (42 papers, 2013 to 2026). "Abnormality of SLC12A5 has been shown to associate with neurological diseases (such as epileptic encephalopathy and Rett syndrome), while the encoded protein plays an important role in regulating morphogenesis of developing neurons and the function of GABAergic synapses through chloride homeostasis." (PMID 36609444, 2023). "Any variant of SLC12A5 that negatively regulates the transporter's expression may, therefore, be implicated in neurological disease." (PMID 31240228, 2019). "KCC2 is encoded by the fifth member of the solute carrier 12 family (SLC12A5) and has remained a poorly understood component in the development and severity of many neurological diseases for many years." (PMID 31240228, 2019).
neurodevelopmental disorder (25 papers, 2016 to 2025). A behavioral and cognitive disorder with onset during the developmental period that involves impaired or aberrant development of intellectual, motor, or social functions. "(i) The identification of a rare new case of neurodevelopmental disorder associated with a previously unknown homozygous variant of SLC12A5." (PMID 38660387, 2024).
tumor (25 papers, 2017 to 2025). "Jiang and colleagues conducted a comprehensive investigation into the role of SLC12A5 across 33 human cancers, demonstrating its potential as a tumour promoter associated with worse overall survival and poor disease‐specific survival." (PMID 38780503, 2024). "Through the analysis of Hi‐C data, we identified a potassium‐chloride co‐transporter SLC12A5 associated with disrupted topologically associating domain which was downregulated in tumour tissues." (PMID 38685685, 2024). "Since patients with immune‐favourable microenvironment and high tumour mutation burden benefited the most from immunotherapy especially immune checkpoint blockade therapy, we further assessed the effect of SLC12A5 on immunotherapy response." (PMID 38685685, 2024). "In all datasets, the primary source of variation (PC1) was likely associated with tumour purity as demonstrated by the expression of neuronal genes, with neuron marker genes like SLC12A5, TMEM130 and SV2B ranking among the top 50 contributors." (PMID 39382765, 2024). "We observed that SLC12A5 expressions were associated with one or more methyltransferases in 21 tumor types." (PMID 34630736, 2021). "Another limitation of this study is that the exact association between SLC12A5 and tumor immunity remains to be elucidated." (PMID 34630736, 2021). "Considering the role of TMB, MSI, methyltransferases, and MMRs in tumor progression, we firstly evaluated the association of SLC12A5 expression with them." (PMID 34630736, 2021). "What is more, we focused on the association between SLC12A5 expression and six tumor-infiltrating immune cells (TIICs) and immunosuppressive molecules in pan-cancers." (PMID 34630736, 2021). "Collectively, these data suggested that tumour‐induced SLC12A5 reduction may contribute to cell depolarization caused by neuronal excitability for tumour growth through reducing GABA's inhibitory signalling." (PMID 38685685, 2024). "A higher frequency of mutations in low SLC12A5 expression group was detected indicating higher tumour mutation burdens which may be beneficial for immunotherapy because of more neo‐antigens production." (PMID 38685685, 2024). "SLC12A5, a neuron-specific potassium-chloride co-transporter, has been reported to promote tumor progression, however, the underlying mechanism remains unclear." (PMID 36609444, 2023). "Additionally, the association of SLC12A5 expressions with tumor mutation burden (TMB), methyltransferases, and mismatch repairs (MMRs) was also analyzed." (PMID 34630736, 2021). "Importantly, robust associations of SLC12A5 with tumor immunity are found in the current study." (PMID 34630736, 2021). "In conclusion, we identified a novel anti-tumor subcluster of M2-like TAMs with high expression of SLC12A5 and ENPP2 as bM2-like TAMs." (PMID 39507421, 2024). "Strikingly, SLC12A5 was mainly expressed in tumour cells and most specifically in NPC‐like tumour cells which characterized stem and progenitor cell signatures and highly expressed GABAA receptor and synaptic genes." (PMID 38685685, 2024). "Meanwhile, three targeted genes (AKT1, MTOR and PIK3CG) of these drugs showed significant upregulation in SLC12A5‐low tumour." (PMID 38685685, 2024). "To comprehensively analyse the function of SLC12A5 in various cancer types, we also explored its expression level between tumour and normal tissue in pan‐cancer data sets." (PMID 38685685, 2024). "Remarkably, pathways in cancer including PI3K‐Akt signalling, focal adhesion, ECM‐receptor interaction, antigen processing and phagosome were activated in tumour with low SLC12A5 expression." (PMID 38685685, 2024). "Of note, tumour with low expression of SLC12A5 presented an immune‐enriched microenvironment with abundance of stromal and proliferative signatures." (PMID 38685685, 2024). "While conventionally recognized as a membrane protein crucial for K‐Cl transport, recent evidence unveils that SLC12A5 is also expressed in the nucleus, exerting a tumour‐promoting role." (PMID 38780503, 2024).
tumor (continued). "We obtained consistent results calculated by ESTIMATE algorithm in which SLC12A5 was significantly positively correlated with tumour purity while negatively correlated with immune and stromal score." (PMID 38685685, 2024). "The majority of T‐cell dysfunction markers were highly expressed in tumours with low expression of SLC12A5, which also had a higher immune evasion score demonstrating the potentials of SLC12A5 on predicting response to immunotherapy." (PMID 38685685, 2024). "Due to the differences in TAD region of SLC12A5, we need CRISPR‐mediated deletion of TAD boundary in the future to determine that this chromatin structure controls the expression of SLC12A5 further influencing the malignance of tumour cell." (PMID 38685685, 2024). "Decreased ratio of anti‐tumour immune infiltrate/pro‐tumour immune infiltrate in tumour with low expression of SLC12A5 indicated a more immunosuppressive microenvironment." (PMID 38685685, 2024). "Tong and colleagues reported that SLC12A5 promotes tumour progression by regulating ER stress and increases ferroptosis resistance in HCC by controlling intracellular redox balance." (PMID 38780503, 2024). "We constructed two SLC12A5 overexpression cell lines to verify the function of SLC12A5 that suppressed tumour cell proliferation and migration in vitro." (PMID 38685685, 2024). "We further confirmed that SLC12A5 promoted tumorigenesis in vivo with subcutaneous xenograft tumor models wherein stably overexpressing SLC12A5 in 22RV-1 cells significantly increased the growth of xenograft tumors." (PMID 36609444, 2023). "Most SLC12A5 protein was localized in the cell surface but some were in the nucleus and the positive nuclear staining rates of SLC12A5 protein were significantly higher in tumor tissue than that in the adjacent normal prostate tissues." (PMID 36609444, 2023). "In this study, we demonstrated that SLC12A5 triggers ER stress to release Ca2+, thereby promoting tumor progression by activating PNCK." (PMID 36645171, 2023). "The tumor growth rate decreased significantly on treatment with VU0240551 targeting SLC12A5 (p < 0.001)." (PMID 36645171, 2023). "We next divided these tumor samples into three groups based on Gleason score [Grade 1:6; Grade 2:7 (3 + 4); Grade 3: 7 (4 + 3)/8/9], and found that the SLC12A5 protein levels were significantly increased in higher Gleason score groups (P < 0.05)." (PMID 36609444, 2023). "Subcutaneous tumor formation experiments were used to validate the tumorigenic effect of SLC12A5 in vivo." (PMID 36645171, 2023). "To examine the role of SLC12A5 in tumor initiation, we next considered the impact of SLC12A5 overexpression or knockdown on tumorigenicity in a nude mouse xenograft model." (PMID 36645171, 2023). "Previous investigations have demonstrated that the expression of SLC12A5 is elevated in multiple tumor types and its elevated expression is usually correlated with a dismal prognosis." (PMID 36645171, 2023). "We evaluated the mRNA levels of SLC12A5 in 33 primary tumor types using the open‐access dataset of The Cancer Genome Atlas (TCGA)." (PMID 36645171, 2023). "The tumor growth rate was faster in the SLC12A5 overexpression group than in the control group, whereas the knockdown of SLC12A5 had the opposite effect." (PMID 36645171, 2023). "Data derived from TCGA, GEPIA, and TIMER databases were utilized to delve into the expressing patterns, prognostic values, clinical significances, and tumor immunity of SLC12A5 in tumors." (PMID 34630736, 2021). "In bladder cancer, SLC12A5 was shown to be highly expressed and its overexpression promoted the proliferation and metastasis of tumor cells via increasing SOX18 expression." (PMID 34630736, 2021). "Herein, we observed that SLC12A5 was significantly overexpressed in various malignancies, and SLC12A5 levels correlated with overall survival, disease-specific survival, and tumor stage of certain cancers." (PMID 34630736, 2021).
tumor (continued). "In the SLC12A5-positive specimens, SLC12A5 was detected in the nucleus and cytoplasm in tumor cells." (PMID 28333147, 2017). "In addition, we found that the expression profiles of FOXD3, F10, and SLC12A5 in immunoassays correlated with the levels of immune cells, neutrophils, and dendritic cells in tumor tissues." (PMID 40785195, 2025). "The expression levels of SLC12A5 positively correlated with IC50 of most anticancer drugs suggested that these drugs may be sensitive in tumour with low SLC12A5 expression." (PMID 38685685, 2024). "In addition, SLC12A5 was also positively associated with GABAA receptor activity and negatively associated with pro‐tumour immune signatures and immunotherapy response." (PMID 38685685, 2024). "However, investigations into the effects of SLC12A5 on tumour viability are still in their nascent stages." (PMID 38780503, 2024). "The expression of SLC12A5 in most of tumour tissues had significantly different degrees of changes compared to normal tissues suggesting that it might have a different biological mechanisms involved in progression of tumour among various cancer types." (PMID 38685685, 2024). "Indeed, the activity of TGF‐beta pathway was also significantly upregulated in tumours with low expression of SLC12A5." (PMID 38685685, 2024). "The significant correlations between SLC12A5 and immune system process suggested that SLC12A5 may be involved in altered tumour microenvironments." (PMID 38685685, 2024). "Moreover, the expression of SLC12A5 was higher in 24 HCC tissues than in paired adjacent non‐tumor tissues, as determined by western blotting (p < 0.01)." (PMID 36645171, 2023). "The mRNA level of SLC12A5 was elevated in 24 tumor types compared with levels in normal tissues." (PMID 36645171, 2023). "PDX tumors were derived from a patient with high SLC12A5 expression in tumor tissues." (PMID 36645171, 2023). "Additionally, SLC12A5 possesses potent oncogenic properties, for example, it promotes tumor growth and metastasis." (PMID 36645171, 2023). "Furthermore, we found that the SLC12A5 mRNA levels were higher in HCC tumor tissues than in paired adjacent non‐tumor tissues." (PMID 36645171, 2023). "However, our study demonstrates that SLC12A5 is also expressed in the nucleus and exerts a tumor-promoting function in the nucleus." (PMID 36609444, 2023). "Taken together, our work revealed that SLC12A5 might serve as a biomarker indicating tumor progression and prognosis and play multifaceted roles in modulating tumor immunity." (PMID 34630736, 2021). "Accordingly, SLC12A5 was highly expressed in 17 out of 24 TWIST1 strong tumor tissue samples, and in 5 out of 18 tumor tissue samples with weak TWIST1 expression; ZFHX4 was highly expressed in 19 out of 24 TWIST1 strong tumor tissues, and in 6 out of 18 tumor tissue samples with weak TWIST1." (PMID 31645542, 2019). "Taken together, our findings indicated that SLC12A5 might function as a tumor metastasis promoting factor in the development and progression of BUC by regulating the NF-κB/MMP-7 signaling pathway." (PMID 28333147, 2017). "SLC12A5 expression significantly correlated with the tumor node metastasis (TNM) stage." (PMID 28333147, 2017). "Notably, the genes identified in our study—FOXD3, F10, and SLC12A5—may also participate in these IRS‐mediated inflammatory pathways in other tumor types." (PMID 40785195, 2025). "However, the exact mechanisms that how SLC12A5 promotes the tumor progression remain largely unknown." (PMID 36609444, 2023). "Then, we investigated the clinical significances of SLC12A5 in pan-cancers, and we noticed that SLC12A5 was higher in advanced tumor stages of COAD, ESCA, and KIRC, while it was lower in advanced tumor stages of PAAD, READ, and TGCT." (PMID 34630736, 2021).
tumor (continued). "We used our own LUAD tissue microarray containing 92 pairs of LUAD and matched non-tumor tissue samples with clinicopathologic information and long-time follow-up records to evaluate the clinical utility of TWIST1, SLC12A5 and ZFHX4 among the LUAD patients." (PMID 31645542, 2019). "Compared with the control group, the tumor volume and tumor weight were smaller in the sh-TWIST1/sh-SLC12A5/sh-ZFHX4 groups." (PMID 31645542, 2019). "Moreover, the amplification of solute carrier family 12, member 5 (SLC12A5) has been observed in CRC, where it promotes tumor progression." (PMID 40918458, 2025). "High genomic alterations in zesto lesions were inversely correlated with putative tumor suppressor genes (MTUS2, DLGAP3, RTN1, CRLF1, SLC12A5, and PDIA2) and positively correlated with APOBEC mutagenesis (APOBEC3C, APOBEC3G, APOBEC3B, and APOBEC3F) and hypoxia-related gene signatures." (PMID 40319462, 2025). "Results from single-cell data analysis showed that compared to tumor cell populations, SLC12A5 expression was more abundant in non-tumor cell populations." (PMID 38886655, 2024). "Here, we reported that SLC12A5 could induce ER stress to promote tumor progression and ferroptosis resistance; alternatively, VU0240551, a SLC12A5 inhibitor, could induce ferroptosis via the down‐regulation of xCT." (PMID 36645171, 2023). "TMZ reduced PBT24 tumor growth, and treatment efficacy was related to significantly increased SLC12A5 expression in PBT24 cells, but there were no such effects on SLC12A5 expression of SF8628 cells." (PMID 35625705, 2022). "Moreover, the presence of “anti-cancer” next to “pro-tumorigenic” within a single tumor only complicates the final conclusion regarding AP-2 role in that cancer (e.g. KRT14 vs GRIA1, SEZ6L, SLC12A5 for AP-2α within PAAD or NTSR1 vs PPEF1 for AP-2γ within LUAD)." (PMID 35361846, 2022). "Chi-square analysis revealed that the level of SLC12A5 in BUC tissues was only highly correlated with pN status (P=0.001) but not with age (P=0.975), gender (P=0.742), tumor size (P=0.781), tumor multiplicity (P=0.292), tumor grade (P=0.130) and pT status (P=0.079)." (PMID 28333147, 2017). "The upregulation of SLC12A5 was not significantly different between GBM5-1F and GBM5-2F tumor cells after treatment (p > 0.05)." (PMID 41012498, 2025).